CRP (C-reactive protein)
Diseases named in the same sentence as CRP in open-access papers (continued):
Sharing a sentence is not in itself a finding about the gene and the disease.
infection (continued). "However, in clinics, these five features covered more types of clinical symptoms: lymphocyte (%) is an immune disorder indicator, neutrophil count represents infection, CRP represents inflammatory response, and both LDH and α-HBDH represent tissue lesions." (PMID 34541519, 2021). "The European Bone and Joint Infection Society (EBJIS) integrated serum CRP as a single serum parameter in their PJI definition as suggestive criterion in their “infection likely” group, while the Infectious Diseases Society of America (IDSA) does not include any serum biomarker in their definition." (PMID 34572314, 2021). "In addition, CRP levels and ESRs reflect the size or activity of inflammatory tissue, and have a good correlation with disease activity during acute inflammation and infection." (PMID 33833340, 2021). "The GPs described how a low CRP value would confirm a suspicion of a self-limiting infection, whereas a high CRP value could convince them of bacterial aetiology." (PMID 34205866, 2021). "Numerous conditions in addition to infections and inflammation, such as trauma, malignancies, and myocardial infarction can stimulate the production of CRP, and it may also have a role in the development of atherosclerosis and cardiovascular diseases." (PMID 35062248, 2021). "SAA is induced and released earlier than CRP upon pathogen infection." (PMID 34205852, 2021). "In addition, observed multisystem inflammatory syndrome in children and adolescents (MIS-C) infection with elevated levels of immunoglobulins, C-reactive protein, ferritin and interleukin-6 indicate possible 4-week post-viral immunisation in the body." (PMID 34685427, 2021). "After trauma and infection, CRP increased significantly, and its application in disease diagnosis can assist in judging whether patients have an inflammatory reaction and bacterial infection." (PMID 35174183, 2021). "CRP is an acute phase reactant that responds rapidly to tissue injury, infection and inflammation." (PMID 34631220, 2021). "Compared to CRP, suPAR is an inferior diagnostic marker for discriminating between infections of bacterial vs. non-bacterial origins." (PMID 34925360, 2021). "In a previous study, the CRP concentration in dogs infected with E. canis increased during the acute stage of infection; this increase could eliminate E. canis in macrophages of infected dogs." (PMID 34566333, 2021). "A high level of CRP indicates that the patient is under a severe systemic inflammatory condition, which might present poor infection control, especially after long-term antibiotics treatment." (PMID 34830626, 2021). "CRP concentrations extremely increased in dogs with all blood parasite infections." (PMID 34566333, 2021). "A favorable outcome was defined as a complete regression of infection (significant decline of C-reactive protein), significant reduction of pain symptoms (VAS Score), improved neurological status or unchanged neurological status in patients without deficits prior to surgery, with ability to walk." (PMID 34439638, 2021). "In PUUV infection, almost all patients have elevated CRP levels." (PMID 35062248, 2021). "Conversely, an unknown entry point of infection, an entry point from an indwelling medical device, and a C-reactive protein concentration of over 161 mg/L on the day of admission were all significantly associated with complications." (PMID 33794783, 2021). "“Positive culture”, purulent drainage”, and increased CRP were considered important symptoms for infections, and it was concluded that such definition will enable a clinician to standardize future research as well as improve the quality of diagnostics tools and treatment algorithms." (PMID 35003964, 2021). "Under normal conditions, the plasma concentration of CRP is generally less than 2.0 mg/L; excess CRP concentrations above 2.0 mg/L can therefore be used to suspect pathologies such as cardiovascular disease, infection, and inflammation." (PMID 33925825, 2021).
infection (continued). "Moderate (pink dots) and severe (blue dots) PC patients had similar CRP levels post infection." (PMID 34944747, 2021). "On days 11 and 14 post operation, the CRP values were higher in the group with an early infection." (PMID 34768504, 2021). "Interestingly, WCC, temperature and CRP, commonly aggregated when defining infections, as well as almost all the cytokines, exhibit different information content." (PMID 34563211, 2021). "The highest mean CRP levels were found in infections of the neck phlegmon (245.8 mg/dL)." (PMID 33532496, 2021). "Furthermore, a SIRCH score equal to three detected seven infections, but five of these would have been missed if clinicians had used the CRP alone at a cut-off of 50 mg/L to indicate imaging (near-miss)." (PMID 34546893, 2021). "CRP is widely used as a marker of inflammation and infection in routine practice." (PMID 34574070, 2021). "Because of the specific mechanism of action of TCZ by which it blocks the Il-6 receptor, the expected rise of CRP levels during infections may be blunted and even normal despite the presence of a serious infective insult." (PMID 33804790, 2021). "CRP is used to indicate infection or chronic inflammatory disease." (PMID 34684116, 2021). "The maximum CRP and the presence of a second peak can be helpful for early infection detection." (PMID 34768504, 2021). "An important parameter for the postoperative assessment of an infection is serum CRP values." (PMID 34768504, 2021). "The protocols regarding line care in our participating centers were similar; in the setting of elevated inflammatory parameters such as leucocytosis and CRP and in the presence of unalarming abdominal status, the source of infection was searched elsewhere, i.e., central and peripheral lines." (PMID 33532890, 2021). "CRP is a general parameter affected by any systemic inflammatory disease (autoimmune disorders, coronary heart disease, active cancer, acute or chronic renal failure, obesity, infections other than joint)." (PMID 34572314, 2021). "C-reactive protein is an indicator of the degree of infection." (PMID 34796234, 2021). "In the present study we describe the detrimental effect of systemic inflammation and infection in mNSCLC receiving PD-1/PD-L1 blockade immunotherapy and suggest a perspective investigation of CRP, ESR and PCT as potential biomarker of response to the immuno-oncological treatment." (PMID 34195086, 2021). "The CRP of patients in the infection group was significantly higher than that of the colonization group (P < 0.05), which suggested that the CRP could be used as an early warning factor for secondary infection after colonization." (PMID 34926395, 2021). "The early rise of CRP levels in neonates after the birth usually leads to suspect infections and to start empiric antibiotics, although CRP may increase up to 20 mg/L during the first days of life." (PMID 33525647, 2021). "In patients with presumed aseptic long bone nonunion and normal CRP levels, the risk of underlying low-grade indolent infection can be as high as 26%." (PMID 33499272, 2021). "Therefore, we assessed CRP as one of the most important parameters indicating the type of infection and the phase response in our study." (PMID 33924694, 2021). "And although CRP was 100% (40/40) sensitive for the infection, its specificity was considered unacceptable for clinical use (144 scans to find 40 infections), and given the ubiquity of back pain, CRP testing in unselected patients would likely result in increased MRI overuse." (PMID 34546893, 2021). "The CRP test is performed in 55% of consultations concerning respiratory illness in out-of-hours care, possibly giving rise to an understanding among the patients that the test is necessary to assess the severity of an infection." (PMID 33792485, 2021). "The CRP level increased in dogs with blood parasite single infections and may be related to the pathogenesis of the infection." (PMID 34566333, 2021).
infection (continued). "A persistent fever and CRP are common clinical indicators of infection." (PMID 33758243, 2021). "CRP is an APP that is used clinically as a marker of inflammation that may denote infection, malignancy or cell stress." (PMID 34485323, 2021). "The strong correlation between the investigated cytokines (including chemokines and growth factors), the oxidative stress parameters and some of the commonly used biomarkers (CRP, D-dimers, NLR, PLR) are in line with the proposed cytokine storm as underlying mechanism of the infection." (PMID 34868558, 2021). "A recent study showed that patients with recurrent infections had increased CRP levels." (PMID 34768700, 2021). "The strengths of this study are the relatively large study population of healthy 1–3-year-old, mainly Caucasian, children from three Western European countries, and the effect of inflammation and/or infection on Zn concentrations that was taken into account by excluding children with CRP > 5 mg/L." (PMID 34835970, 2021). "Several studies have shown that CRP may provide protection against infection by the gram-positive pathogen Streptococcus pneumoniae, Salmonella enterica serovar Typhimurium, and Haemophilus influenza." (PMID 33804790, 2021). "Infections and non-infectious diseases, such as malignancies and inflammatory disease, can cause increased CRP production." (PMID 33233806, 2020). "Synthesis and release of CRP, which is an acute phase reactant, is dependent on the interplay of pro-inflammatory cytokines which are released as a part of an inflammatory response and this decreases its specificity for detecting infections." (PMID 32076032, 2020). "who found that CRP ≥ 5 mg/L was a positive predictor for influenza A and/or B infection." (PMID 33174788, 2020). "CRP is a positive acute-phase reactant synthesized by the liver, induced by cytokines like IL-6, and its level in the blood increases within hours in response to inflammation and infection." (PMID 31947993, 2020). "NLCR, PCT and CRP were markedly different between the non-infection and HAP groups." (PMID 32527243, 2020). "The level of C-reactive protein was important to evaluate the infection." (PMID 32867706, 2020). "Thus, during late-stage infection, two different structural conformations of CRP are required for protection." (PMID 33117400, 2020). "CRP, an acute-phase protein, increases quickly related to inflammation or infection." (PMID 33363024, 2020). "In early stage of infection, the CRP level may be low, but serial measurements can give more helpful results and can be useful in deciding when to terminate antibiotic treatment." (PMID 33233806, 2020). "Even these severely immunocompromised patients show an acute phase reaction with increased serum CRP levels in response to infections, and they also show significantly altered levels of a wide range of other mediators, especially regulators of inflammation as well as several other biomarkers." (PMID 32707721, 2020). "In our sample of war-affected adolescents, CRP levels were only mildly elevated (mean = 1.42 mg/L, median = 0.63 mg/L), ranging from 0.05 to 9.98 mg/L (excluding values > 10 mg/L, or 3% of data points, which likely indicated the presence of active infection)." (PMID 30797045, 2020). "A sensitivity analysis including only the 55 patients with microbiologically confirmed infection showed significant AUC [95% CI] for the CRP (0.80 [0.65–0.96]) and the platelet/d-dimer ratio (0.73 [0.59–0.87]), and also for the NLR (0.71 [0.52–0.86]) and LDH (0.73 [0.55–0.90])." (PMID 33033405, 2020). "Pre-modified CRP could also be therapeutically beneficial for infections with antibiotic-resistant pneumococcal strains and for infections with other bacterial species that use host proteins to evade complement-mediated killing." (PMID 33117400, 2020). "Parameters associated with an active infection, such as CRP and white blood cell count, were not significantly correlated with cytokines and chemokines in SEBC samples." (PMID 31998415, 2020).
infection (continued). "The overcompensating immune reaction which often triggers SIRS after surgery, causes detrimental deterioration during acute pancreatitis, or mediates a cytokine storm after infection, could be dampened with CRP apheresis." (PMID 32932587, 2020). "Multiple logistic regression analysis with backward selection on the discovery cohort showed that elevated levels of MRP8/14 (log10 OR = 7.7, 95% CI = 3.2–18.5) and CRP (log10 OR = 5.1, 95% CI = 1.7–14.7) were predictive for acute KD over an infection (p < 0.001)." (PMID 32775314, 2020). "Previous studies have also described a significant association between pre-engraftment CRP increase not caused by documented infection and increased risk of later GVHD as well as non-relapse mortality." (PMID 32707721, 2020). "Since the presence of infection could cause higher biomarker concentrations, especially of CRP, IL-6, PCT, and IPF, the data were analyzed excluding patients who developed infection during the first 3 days after CS." (PMID 37360622, 2020). "Current evidence suggests that serial CRP monitoring cannot reliably determine infection control in two-stage revision; however, the role of CRP in assessing the success in DAIR and single-stage revision procedures remains unclear." (PMID 32089975, 2020). "More CRP or more fibrinogens increase infection probability." (PMID 32712786, 2020). "OB was similar to the CRP for the discrimination of patients with severe infection." (PMID 33213370, 2020). "What was more, when infantile iKD were compared with ADV infection, Hb, CRP, N%, and PLT could work as indications of iKD." (PMID 32923416, 2020). "Re-elevation of CRP without clinical manifestations was considered as a relapse if other causes such as infection were excluded and the treatment was intensified." (PMID 32264967, 2020). "Indeed, IL-6 and C-reactive protein, indicators of infection, are elevated in individuals who report long sleep duration." (PMID 32671413, 2020). "C-reactive protein (CRP) is a useful marker for monitoring infection and inflammation." (PMID 33193910, 2020). "C-reactive protein is an acute-phase reactant protein which is synthesized mainly by hepatocytes but also by blood monocytes in response to infection or inflammation upon stimulation by proinflammatory cytokines as interleukin-6 (Il-6) and tumor necrosis factor-α (TNF-α)." (PMID 32307587, 2020). "CRP levels rise sharply during the early phase of an infection, whereas AGP levels gradually increase so timing of testing may be critical to assess levels." (PMID 33187486, 2020). "These variations in the median concentrations of IL-6 and CRP among neonates infected by different microorganisms might be due to the difference in the host inflammatory response during infection by different microorganisms." (PMID 33233806, 2020). "Due to their dramatic systemic upregulation upon infection (i.e. by 500‐ to 1000‐fold), sPRRs have been termed ‘inflammation markers’, with some of them being extremely valuable in daily clinical practice (e.g. CRP, high‐sensitivity CRP and SAA)." (PMID 32246830, 2020). "A total of 51 patients (28.3%) with infections showed a normal CRP level below 5 mg/L." (PMID 32095896, 2020). "Finally, to get a comprehensive mapping of the proteome changes during an infection, we focused the multivariate analysis on the plasma protein profiles and their relationship with the CRP." (PMID 32576278, 2020). "Overall about 41% of the children had infection or inflammation (CRP > 5 mg/L) at baseline." (PMID 32724619, 2020). "Moreover, increased CRP value is commonly evidenced in patients with cancer or infections, although decreasing albumin values occurs frequently during serious infections in otherwise healthy patients." (PMID 32344777, 2020). "C-reactive protein (CRP) is produced by hepatocytes following acute tissue injury or infection." (PMID 33054839, 2020).
infection (continued). "Additionally, early renal injury was significantly associated with C-reactive protein (CRP) and neutrophil ratio (NER) indicating that early renal injury was precipitated by severe infection." (PMID 33330565, 2020). "As infectious etiologies were most often (55%) the reason for extremely high CRP values in humans, it is recommended to rule out infections as a first step of the diagnostic workup." (PMID 32434519, 2020). "Due to relatively high NPV, it seems that CRP beyond first 48 hours may be applied for initial exclusion of the diagnosis of infection." (PMID 32127631, 2020). "Among patients admitted to ICUs with suspected infection, frail patients were more likely to be older and have more comorbidities; frail patients were also less likely to be discharged home and had lower temperature and C-reactive protein levels." (PMID 33218303, 2020). "Surgeons have traditionally used CRP to determine if the infection has resolved." (PMID 32089975, 2020). "In contrast, elevated CRP levels have been found within 6–8 h of infection and peak after 36–50 h." (PMID 32160878, 2020). "Only peak CRP beyond first 48 hours was associated with infections (p = 0.038) with AUC, positive and negative predictive value of 0.728, 42.9% and 92.2%, respectively (cut-off: 142.7 mg/L)." (PMID 32127631, 2020). "The higher the ratio between fibrinogen and CRP, the less likely is an infection." (PMID 32712786, 2020). "However, the reported negative predictive value for EOS was 99.7%, which suggests that CRP is more useful for ruling out infection when normal serial values are obtained." (PMID 33419284, 2020). "CRP concentration increases during infection and trauma, and minor elevations in CRP may be indicators of future cardiovascular disease." (PMID 32272662, 2020). "Therefore, at the terminal stage of infection, the environmental glucose concentration is so low that the intracellular concentration of cAMP is high enough to activate CRP, and thereby promote the CRP-dependent pla expression." (PMID 33202679, 2020). "We, therefore, aimed to investigate whether CRP can predict influenza A or B infection in primary care patients presenting with ILI." (PMID 33174788, 2020). "Furthermore, CRP at 0 hour can be raised due to a severe infection, but it also can be raised in the days following resuscitation of CA50,51, reflecting a systemic inflammatory response." (PMID 32103031, 2020). "CRP is an acute-phase protein that serves as an early marker of inflammation or infection." (PMID 33312067, 2020). "In the early phase of an infection or inflammation, CRP can rise before ESR does." (PMID 32616029, 2020). "PTX3 increases within 6–8 h of response to infection, compared to 24–30 h for CRP." (PMID 33301518, 2020). "On the other hand, in the absence of infection, systemic inflammation and elevated C-reactive protein (CRP) have also been associated with QT prolongation." (PMID 32839385, 2020). "CRP is a sensitive, reliable and early indicator of inflammation and infection." (PMID 32932587, 2020). "The higher the ratio between serum thrombocytes and CRP, the less likely is an infection." (PMID 32712786, 2020). "We evaluated the synovial cell count, synovial polymorphonuclear cell percentile (% neutrophils), serum white blood cell (WBC), erythrocyte sedimentation rate (ESR), and C-reactive protein (CRP) in order to determine their association and predictive power in a true infection." (PMID 32670713, 2020). "Third, our nomogram only predicts the occurrence of MDRO colonization or infection, but does not implicate any causal relationship between gender, CRP, Pitt score and occurrence of MDRO colonization and/or infection." (PMID 32430043, 2020). "The mean IPF% values were compared to mean CRP levels in patients with infection." (PMID 32821576, 2020). "CRP serum level may rapidly increase as a consequence of tissue damage or necrosis; infection (viral, bacterial); parasitic invasion; inflammation; aging or malignant neoplasia." (PMID 32859040, 2020).